ALB (albumin)
Diseases named in the same sentence as ALB in open-access papers (continued):
Sharing a sentence is not in itself a finding about the gene and the disease.
cancer (continued). "More recently, the C-reactive protein (CRP) to albumin ratio (CAR) has been demonstrated to be associated with survival outcomes in cancer patients." (PMID 37509622, 2023). "In a cohort of over 150 patients suffering from OSCC, the increase in the fibrinogen-to-albumin ratio was reported to be an independent prognostic factor, negatively associated with the cancer-specific survival of the patients considered." (PMID 37763165, 2023). "Preoperative inflammatory markers, such as Glasgow prognostic score, modified Glasgow prognostic score and C-reactive protein to albumin ratio, were shown to be associated with prognosis in patients undergoing pancreatectomy for cancer." (PMID 37322265, 2023). "In the present study, this association remained significant after adjustment for cancer, BMI, albumin level, and ICU referral, suggesting B12 is an independent marker of poor prognosis." (PMID 38146346, 2023). "The nutritional risk index (NRI), which is based on weight and albumin levels, is closely associated with the prognosis of many cancers." (PMID 36441260, 2023). "Higher neutrophil levels and lower albumin levels likely cause a poor prognosis for cancer patients." (PMID 37836573, 2023). "Low levels of serum ALB, a nutritional status indicator, have been associated with poor prognoses for different cancers." (PMID 37941546, 2023). "Several studies have demonstrated that low serum albumin levels are associated with a poor prognosis in patients with various cancers." (PMID 36975429, 2023). "Functioning as a potent antioxidant, albumin aids in neutralizing free radicals—unstable molecules responsible for cellular damage and heightened cancer risk." (PMID 37987317, 2023). "Albumin level, platelet count and lymphocyte count were also associated with survival, but the effect direction differed by cancer type." (PMID 35444210, 2022). "Cumulative exposure to diverse proinflammatory cytokines in cancer-related chronic inflammation causes hyperglobulinemia and suppression of albumin synthesis in the liver." (PMID 35629255, 2022). "In cancer, the progression of the disease is associated with increasing systemic inflammation, leading to hyper catabolism and decreased serum albumin levels." (PMID 34519976, 2022). "The primary aim of our study was to investigate differences between men and women in the association between self-assessed appetite and measured albumin levels in palliative cancer patients." (PMID 35629338, 2022). "In accordance with other studies analyzing pretreatment albumin as an outcome prognosticator in cancer patients, low serum albumin was associated with a worse survival in our cohort." (PMID 35052870, 2022). "Previous studies have demonstrated that pretreatment serum albumin is associated with short life expectancy in cancer patients." (PMID 35241740, 2022). "We used cancer as another means to examine this independent association of low albumin and disease severity." (PMID 35268297, 2022). "As cancer-associated fibroblasts are implicated in stromal collagen modeling, we also tested the effect of activated fibroblasts on albumin transport using an in vitro transwell assay." (PMID 35486732, 2022). "In conclusion, serum ALB is an easily obtained effective risk-stratification biomarker and is helpful for clinical decision-making regarding human cancers." (PMID 36531036, 2022). "Both poor nutrient status and low albumin level, which are common in cancer patients, are associated with an increased risk of pulmonary complications." (PMID 35055366, 2022). "Serum albumin concentrations are associated with survival in a range of medical conditions, including cancer." (PMID 35398717, 2022). "Since our recent findings have shown specific MAGE-modified blood proteins, further studies on spacial modifications of immunoglobulin and serum albumin are of high relevance in cancer and diabetic conditions associated with protein modification by MAGE." (PMID 36361822, 2022).
cancer (continued). "Our primary aim was to investigate sex differences in the association between appetite and albumin levels in palliative cancer patients." (PMID 35629338, 2022). "It has been known that most patients with malignant tumor exhibit weight loss and decreased albumin levels." (PMID 34996486, 2022). "In the pathological state of cancer, albumin consumption increases, and low albumin weakens immune defense mechanisms, resulting in a vicious circle associated with cancer." (PMID 36406359, 2022). "Cancer cachexia occurs in 80 percent of patients diagnosed with advanced cancer; it is commonly accompanied by low levels of albumin, and is associated with worse outcomes." (PMID 35629338, 2022). "The HALP score, which is the combination of hemoglobin, albumin, lymphocyte, and platelets has been confirmed as an important risk biomarker in several cancers." (PMID 35020581, 2022). "In general, serum albumin level and BMI are the key variables that can reflect the survival risk of malignant tumor patients." (PMID 35392884, 2022). "Studies have shown that serum albumin and lymphocytes are independent prognostic risk factors for cancer patients." (PMID 35297197, 2022). "Reduced pre-albumin levels have also been documented in cancer patients and are associated with a poor prognosis." (PMID 35033080, 2022). "Serum albumin, a commonly used parameter of nutritional status, is inversely associated with prognosis in various cancers." (PMID 35603156, 2022). "Univariate Cox regression analysis showed that AKI-RRT, age, chronic liver disease, malignancy, low baseline serum albumin, and SOFA score on admission were associated with 1-year mortality." (PMID 35870022, 2022). "In recent years, the Fibrinogen to pre-albumin ratio (FPR) has been reported in many studies to be significantly associated with the prognosis of various cancers." (PMID 35033080, 2022). "Low albumin level had been proved to associated with worse survival in patients with various cancer." (PMID 36337651, 2022). "A prognostic nutritional index, based on serum albumin levels and peripheral lymphocyte count, has been confirmed to be significantly associated with various cancers." (PMID 35872955, 2022). "We systematically analysed eight related indicators of peripheral blood measurement, where TP level mainly reflects the loss of protein caused by renal lesion and serum ALB is also be greatly reduced in cancer patients." (PMID 36547129, 2022). "Serum albumin was negatively correlated with all four in pan-cancer and most of the subgroup analyses, which suggests that serum albumin is associated with distinct inflammation states." (PMID 35393553, 2022). "In cancer patients with normal liver synthesis function, ALB is often associated with the patient's nutritional status and inflammation level." (PMID 35965687, 2022). "As prognostic factors for obstructive CRC, performance status, serum albumin level <4.0 g/dL, and resection of T4 and R1 cancers (cancer positive at cut end) were also independent risk factors for recurrence." (PMID 35086523, 2022). "As the 50th quintile of albumin concentrations (46 g/L) was chosen to be the reference, the HRs of overall cancer risk related to albumin levels rise sharply when albumin levels were below 46 g/L." (PMID 34041866, 2021). "Our findings suggested that pre‐diagnostic albumin levels were inversely associated with overall cancer risk." (PMID 34041866, 2021). "Previous published studies have revealed that low levels of lymphocyte, albumin, and hemoglobin were associated with poor survival in various cancers." (PMID 33974528, 2021). "In a next step, we pooled the information provided by albumin and Kyn/Trp, both being associated with cancer exhaustion, to a combined score for cancer exhaustion." (PMID 34884980, 2021). "In the cancer-bearing state, it is well known that albumin consumption by cancer cells causes albumin depletion." (PMID 34473762, 2021).
cancer (continued). "In conclusion, our findings suggest that pre‐diagnostic serum albumin is inversely and linearly associated with cancer risk among the Chinese population." (PMID 34041866, 2021). "In general, individuals with higher albumin levels were at decreased overall cancer risk among both the normal‐weight and overweight population." (PMID 34041866, 2021). "Investigators have demonstrated that neutrophils, lymphocytes, plasma fibrinogen and serum albumin play prominent roles in cancer-related inflammation and are considered to be associated with patient outcomes." (PMID 34234871, 2021). "Affinity Affibody-ABD fusions to cancer-associated antigen and albumin, as well as their biodistribution, are influenced by the position where a chelator is coupled." (PMID 34200197, 2021). "Referred to the median of albumin concentrations, HRs of overall cancer risk increased sharply when albumin concentrations were below 46 g/L." (PMID 34041866, 2021). "Based on a large prospective cohort study, this analysis displayed the associations between pre‐diagnostic serum albumin and cancer risks." (PMID 34041866, 2021). "Numerous studies cited in our review show that serum albumin-based nanovehicles possess a great potential in cancer diagnostic and therapeutic applications." (PMID 34869202, 2021). "The decreased level of albumin correlated with the production of pro-inflammatory cytokines, such as interleukin-6, a cytokine associated with progression of cancers." (PMID 33608012, 2021). "As the established risk factors played a leading role in the development of cancer, the effect of albumin was still significant." (PMID 34041866, 2021). "Two previous studies have explored the association between cancer risk, mortality, and metabolic markers including albumin, bilirubin, and uric acid, which were all considered as non‐nutrient antioxidants of physiologic importance." (PMID 34041866, 2021). "Low ALB levels represent inadequate nutritional and/or aggravated hypercatabolic states with resultant weight loss, which is a key determinant of cancer cachexia, a well-established poor prognostic factor for PAC patients." (PMID 33927759, 2021). "More recently, a large cohort study conducted on > 1000 cancer patients in the framework of the Vienna CAT study specifically evaluated the association between low serum albumin and increased TE risk." (PMID 34521927, 2021). "Studies have shown that lower albumin levels before surgery increase the overall mortality and risk of cancer-specific deaths." (PMID 34257601, 2021). "While albumin levels have mostly been inversely associated with the risk of cancer, uric acid has been associated with an increased risk of cancer and increased cancer-related mortality." (PMID 34771701, 2021). "This is the first prospective cohort study to evaluate the association between pre‐diagnostic serum albumin and cancer risk." (PMID 34041866, 2021). "Low albumin levels are associated with poor long-term survival rates in various types of cancer and are more common in patients with advanced cancer." (PMID 34765598, 2021). "The fact that plasma levels of CRP and albumin are routinely measured in cancer older patients underlines the clinical applicability of our present results." (PMID 34944774, 2021). "These genes are associated with several cancers, such as ALB that is associated with lymph node metastasis in lung squamous cell carcinoma." (PMID 34154655, 2021). "Both serum albumin concentration and BMI are important parameters that can reflect the risk of survival in patients with malignancies." (PMID 34585849, 2021). "After controlling for pertinent risk factors, results suggested that serum albumin was inversely associated with overall cancer risk with a significant linear association." (PMID 34041866, 2021). "Various studies have looked at the association between other circulating antioxidants (i.e., albumin and uric acid) and risk of cancer with mixed results." (PMID 34771701, 2021).
cancer (continued). "This study was conducted to evaluate the association between pre‐diagnostic serum albumin and cancer risk among Chinese." (PMID 34041866, 2021). "In fact, healthy individuals with low AGR as a result of underproduction of albumin and over production of globulin have a higher risk for major cancer types, especially liver and hematological cancers." (PMID 33639645, 2021). "Results from a cohort study indicated that lower albumin levels were associated with an increased risk of new cancer diagnosis within a year." (PMID 34041866, 2021). "Variables associated with LGIB-related mortality were the presence of cancer, heart rate > 100 beats/min, blood urea nitrogen level ≥ 30 mg/dL, an international normalized ratio > 1.50, and albumin level ≤ 3.0 g/dL." (PMID 34844565, 2021). "Cox proportional hazards models and restricted cubic spline (RCS) analyses were used to evaluate the association between pre‐diagnostic serum albumin and cancer risk." (PMID 34041866, 2021). "Our findings suggest that pre‐diagnostic serum albumin is inversely and linearly associated with cancer risk among the Chinese population." (PMID 34041866, 2021). "To date, there is a growing evidence showing that high albumin levels or low globulin levels are associated with a better prognosis in patients with various types of cancer, including the chronic infectious TB disease." (PMID 34206598, 2021). "For instance, albumin concentration is associated with weight loss in cancer patients and serum albumin levels collected at admission to a hospital can predict weight loss in children during their stay." (PMID 33639645, 2021). "Inflammation-based scores consisting of CRP and ALB as the Glasgow prognostic score have been proven to be significantly associated with survival in various cancers." (PMID 33676467, 2021). "Albumin NPs can be decorated with a variety of targeting ligands to give additional specificity to cancer cell-associated receptors." (PMID 31858848, 2020). "The univariate analysis revealed that old age, female sex, a low BMI, and high FFA and albumin levels were associated with an increased risk of cancer." (PMID 31773260, 2020). "Nab-paclitaxel, a typical coupling drug in a nano-albumin-bound form causing macropinocytosis, has been applied in the cure of a large amount of cancers." (PMID 33542897, 2020). "Apart from site of primary cancer, serum albumin is the other independent risk factor for mortality in this study." (PMID 32245389, 2020). "Albumin and globulin are associated with immune responses in cancer patients as well as the nutritional status." (PMID 32974174, 2020). "While the mechanism of protein synthesis and distribution is complex, albumin levels have been associated with liver function and patient survival in critically ill patients and cancer patients." (PMID 33101412, 2020). "The findings of many studies reveal that lower serum albumin leads to a high risk of deterioration and poor prognosis in cancer patients." (PMID 33014783, 2020). "Many indicators based on inflammation and nutritional status have been used to predict the prognosis of cancer, including the Glasgow prognostic score, modified Glasgow prognostic score, C-reactive protein–albumin ratio, and Geriatric Nutritional Risk Index." (PMID 33376729, 2020). "Albumin levels are associated with complications and mortality in patients with cancer following surgery." (PMID 32104193, 2020). "Prospective studies directly addressing the relationship between skeletal muscle function, gene expression, and serum albumin would be required to validate the clinical utility of serum albumin in identifying those at risk of cancer-induced muscle dysfunction." (PMID 32550263, 2020). "Accordingly, several studies have reported an increased risk of cancer mortality associated with low serum albumin concentrations." (PMID 32353950, 2020).
cancer (continued). "Low p-albumin concentrations seem to be associated with increased cancer, cardiovascular, and all-cause mortality rates in middle-aged males." (PMID 33226880, 2020). "The association between albumin levels and the prognosis of patients has been reported in various cancers, including ovarian, colorectal, and lung cancers, in addition to UC." (PMID 32974174, 2020). "Serum albumin (ALB), which reflects the nutritional status, has also been proven to be associated with poor prognosis in many cancers." (PMID 31677642, 2019). "CRP has been reported to be associated with reduced serum albumin, resulting in progressive weight loss, poor performance, and higher mortality in cancer patients with systemic inflammation." (PMID 30941358, 2019). "Inflammatory markers such as CRP, albumin, neutrophil, and lymphocyte count have been associated with mortality in numerous cancer types." (PMID 31096693, 2019). "A systematic review of the epidemiological literature reveals the significant prognostic role of pretreatment serum albumin in cancer and baseline albumin levels that are recommended for risk stratification." (PMID 30925910, 2019). "In the additional analyses with further adjustments for age, sex, history of CVD, serum albumin, hemoglobin, eGFR, and pathologic findings of GN, the risk of cancer was 15.7 (95% CI: 4.82–51.30; p < 0.01)." (PMID 31626671, 2019). "In a multivariate analysis, age, primary cancer, and albumin were significantly associated with survival." (PMID 31930179, 2019). "Many inflammatory indexes (PCR, Platelet/Lymphocyte ratio - PLR -, albumin levels, fibrinogen levels, etc.)obtained from blood tests were associated with outcomes of many cancers." (PMID 30785697, 2019). "In our study, male gender, ASA ≥3, weight loss, open wound, relapse of cancer metastasis and laboratory data including low serum albumin, low Na level and elevated C‐reactive protein (CRP) levels were identified as predictors." (PMID 29863168, 2018). "Specifically, we find that plasma redox imbalance caused by albumin oxidation promotes inflammation-independent NETosis and cancer metastasis within the lungs." (PMID 30504805, 2018). "In this study, we used a recombinant form of human albumin—Recombumin (rHSA, Albumedix Ltd.)to demonstrate the potential of thiol‐gold linked protein‐metal complexes for cancer therapeutics." (PMID 29729206, 2018). "Insulin was studied for its anti-lipolytic effects in 138 patients with advanced GI malignancies and cancer cachexia (weight loss 2–3% of baseline and albumin < 36 g/L)." (PMID 30482179, 2018). "RDW is also associated with nutritional indicators, including albumin, iron, folate, and vitamin B12 in patients with cancer." (PMID 29190934, 2017). "The ratio of C-reactive protein to albumin, as a novel inflammation-based prognostic score, is associated with outcomes in cancer and septic patients." (PMID 28069031, 2017). "The PNI is a combined nutritional-inflammatory score based on serum albumin levels and the lymphocyte count that reflects the immunological nutritional condition and that measures the risk of several types of cancer in patients." (PMID 28607442, 2017). "GPS and mGPS were thus generalized from the combination of CRP and albumin; as new inflammatory markers, they have been proved to be useful prognostic factors to predict the risk of cancer." (PMID 28676731, 2017). "Decreases in serum bilirubin and albumin levels are associated with poorer prognoses in some types of cancer." (PMID 28476041, 2017). "In this study, all liver parameters, i.e. GGT, AST, ALT, BChE, albumin and bilirubin were significant risk predictors for all-cause mortality in the total cancer patient cohort." (PMID 29113384, 2017). "The inclusion of unselected patients with various types of cancer enables a rather unbiased approach for the investigation of liver parameters especially BchE and albumin underlining the relevance of this clinical finding." (PMID 29113384, 2017).